RNU7-80P (RNA, U7 small nuclear 80 pseudogene)
Synonyms: U7.80
Gene: Small nuclear RNA gene on chromosome 1 (67,772,593 to 67,772,653, reverse strand). Ensembl gene ENSG00000238778.
Homologues: Orthologues: chimpanzee U7 (100% identical), macaque U7 (92% identical), pig U7 (79% identical). Paralogues in human: RNU7-79P (92% identical), RNU7-67P (89% identical), U7 (89% identical), RNU7-59P (87% identical), RNU7-11P (85% identical), RNU7-26P (85% identical), RNU7-55P (85% identical), RNU7-62P (85% identical), RNU7-84P (85% identical), RNU7-24P (84% identical), RNU7-2P (84% identical), RNU7-48P (84% identical), and 143 more.